IL6 (interleukin 6)
Diseases named in the same sentence as IL6 in open-access papers (continued):
Sharing a sentence is not in itself a finding about the gene and the disease.
uveitis (continued). "The activation of glucocorticoid receptor isoform alpha (GRα) by CS results in anti-inflammatory effects in uveitis, suppressing the production of pro-inflammatory cytokines, such as IL-1, IL-6, and TNF-α, by blocking their transcription." (PMID 40433375, 2025). "The network showed that LXD exerted therapeutic effects upon valuable targets participated in the genesis and development of uveitis, including Notch1, IL-6, IL-2, TNF, and IL-10." (PMID 40918405, 2025). "Research has found that PGN can significantly increase the production of IL-1β, IL-6, and IL-23 by dendritic cells (DCs) and enhance their ability to promote the generation of IL-17+ uveitis-producing T cells." (PMID 39858245, 2025). "Elevated levels of IL-6 have been detected in the serum and aqueous humor of uveitis patients, indicating its involvement in disease activity and its potential utility as biomarker for disease monitoring and therapeutic response." (PMID 40433375, 2025). "These ongoing studies further support the potential use of IL-6-targeted therapies for patients with uveitis complicated by persistent or vision-threatening ME." (PMID 41424786, 2025). "For uveitis, the pathogenesis is associated with the activation of Th1 and Th17 cells, which secrete inflammatory cytokines such as TNF-alpha, IL-17, IL-23, and IL-6, driving the inflammatory response." (PMID 40038580, 2025). "The roles of IL-10 and IL-6 have been extensively explored in various ocular diseases, including uveitis, where cytokine analysis has been widely proposed for differential diagnosis." (PMID 40433375, 2025). "Systemic inhibition of IL-6 has demonstrated efficacy in alleviating uveitis in both animal models and humans." (PMID 39497001, 2024). "Apart from playing a crucial role in the initiation of uveitis and consequent ME via these inflammatory pathways, IL-6 can also contribute to the occurrence of ME through alternative mechanisms." (PMID 39272767, 2024). "Various cytokines, including Interleukin-6 (IL-6), play a significant role in the inflammatory cascade of uveitis." (PMID 39497001, 2024). "In experimental autoimmune uveitis (EAU) mouse models with IL-6 knockout, uveitis development was significantly suppressed." (PMID 39449328, 2024). "Previously, topical application of gabapentin downregulated IL-6 in experimental uveitis giving credence to our findings." (PMID 39502139, 2024). "Several reports have already shown that IL-6 levels are increased in the aqueous humor in patients with uveitis." (PMID 38232093, 2024). "Many recent reports have examined the relationship between uveitis and IL-6 level and several functions of IL-6 have been identified, allowing the development of biomedicines against non-infectious uveitis." (PMID 38232093, 2024). "IL-6 is a major player in uveitis, the presence of IL-6 receptors on retinal vascular endothelial cells suggests that elevated serum levels of this cytokine can produce significant visual morbidity." (PMID 39075390, 2024). "IL-6 induces inflammation in the eyes, partly by promoting Th17 cell differentiation through IL-6 in uveitis." (PMID 39839649, 2024). "Intravitreal anti-IL-6 activity treatment for macular edema in uveitis patients is already under investigation (NCT05642325)." (PMID 39497001, 2024). "This study investigated properties and intraocular distribution of hyperreflective particles (possibility of vitreous inflammatory cells) on WOCT and the correlations with IL-6 levels and cell characters in uveitis patients." (PMID 38232093, 2024). "An additional study on uveitis patients reported some differences (age, presence of systemic disease, number of flare-ups) observed between the high-serum IL-6 group (≥5 pg/mL) and the normal-serum IL-6 group (<5 pg/mL)." (PMID 36902507, 2023). "The vitreous level of IL-6 has also been shown to be an effective indicator in diagnosing intraocular lymphoma, which often masquerades as uveitis, thus making it difficult to diagnose." (PMID 36902507, 2023).
uveitis (continued). "TNF-α-induced uveitis in rats is associated with IL-6; therefore, TNF-α and IL-6 inhibition in the AqH suppresses uveitis development." (PMID 36977246, 2023). "Outside of uveitis, elevated levels of IL-6 have also been found in multiple ocular diseases, including central vein occlusion." (PMID 36902105, 2023). "It has been shown that ANXA1 (Ac2-26) reduces the production of proinflammatory cytokines, such as TNF-α, IL-1β and IL-6, in LPS-induced uveitis." (PMID 36544058, 2023). "Literature review of studies of patients with refractory uveitis-related cystoid macular edema treated with IL-6 inhibitors." (PMID 36902105, 2023). "This study retrospectively determined the relationship between vitreous IL-6 levels and clinical and laboratory data collected from uveitis patients." (PMID 36902507, 2023). "Another relevant cytokine in the pathophysiology of both entities is IL6, related to the intraocular immune response in several types of uveitis and involved in DED pathology, even correlated with eye pain in the latter." (PMID 36715869, 2023). "In summary, in BD uveitis pro-inflammatory cytokines such as Il-6, TNFα, ΙFNγ, and IL-1ra are increased in AH." (PMID 37297843, 2023). "The levels of EGF, fractalkine, IL1-β, IL-17A, IL-1RA, IL-2, IL-23, IL-8, IP-10, TNF-α and IL-6 in patients with uveitis in their active phase were independent to their counterpart levels in plasma, the difference being statistically significant (p < 0.05)." (PMID 36498608, 2022). "Elevated intraocular levels of IL-6 were found repeatedly in uveitis of diverse etiology (including ocular toxoplasmosis, viral uveitis, Fuchs uveitis syndrome, and Behcet’s uveitis), as well as in ocular fluids of children with uveitis." (PMID 35646978, 2022). "This helps explain the similar expression level of IL-6 in both OT and uveitis patients in our study." (PMID 35646978, 2022). "Previous study have shown increased IL-6 and IL-8 in the intraocular samples of patients with TU, viral uveitis, Fuchs iridocyclitis, ocular Behcet disease and pediatrics uveitis." (PMID 35061677, 2022). "Again, anti-TNF-α or anti-IL-6 treatment improves the induced pathologies in diverse uveitis models." (PMID 36371417, 2022). "IL-6 is a pleiotropic cytokine that is involved in the pathogenesis of many immune-mediated diseases, such as uveitis." (PMID 36313265, 2022). "Analysing their outcomes, they showed increased levels of TNF-α and IL-6 in four out of five eyes with uveitis, which is contradictory to our study." (PMID 36498608, 2022). "Anti-IL6 therapies are currently used to treat conditions like uveitis, neuromyelitis optica, and most recently, COVID-19 pneumonia." (PMID 35313341, 2022). "Studies have shown that levels of the cytokines IL-6 and IL-10 are elevated in the aqueous humor of patients with uveitis." (PMID 36761168, 2022). "Of note, most of these investigations have compared active with inactive uveitis or a healthy control group showing increased serum levels of different cytokines in the active group, such as the IL-8, IL-6, TNF-α, IL-17, IL-21, IL-23." (PMID 36498608, 2022). "Cytokines tumour necrosis factor-alpha (TNFα), interleukin (IL)-6 and monocyte chemoattractant protein-1 (MCP-1) can be produced by activated macrophages during uveitis and are involved in the associated inflammatory responses." (PMID 33671954, 2021). "In the case of PVRL, this led to the suggestion for screening of suspected uveitis cases by evaluating IL-10 values and IL-10/IL-6 ratio before vitreous biopsy." (PMID 33146828, 2021). "The efficacy of IL-6 inhibitors was supported in various clinical studies including a phase 2 clinical trial (STOP-Uveitis, tocilizumab)." (PMID 33671954, 2021). "On the other hand, studies have shown that IL-6 has a major role in the pathology of uveitis, glaucoma, retinal vein occlusion, macula edema, and diabetic retinopathy." (PMID 34608867, 2021).
uveitis (continued). "We confirm that inflammation is present in the quiescent stages of uveitis, IL-6 being the most outstanding cytokine in this process." (PMID 33921773, 2021). "IL-6, TNF-α, and IL-1β are also associated with dry eye, uveitis, proliferative diabetic retinopathy, and diabetic macular edema." (PMID 34285659, 2021). "Cytokines were clustered in two major groups: the first one included cytokines with the highest fold difference in concentrations between patients with uveitis and controls: IL-6, IL-8, IFNγ, TNFα, IP-10, G-CSF, IL-1ra." (PMID 32210963, 2020). "Interleukin-6 (IL-6) is a pro-inflammatory cytokine that is secreted under inflammatory conditions, including in the context of uveitis." (PMID 33505989, 2020). "IP-10, IFNγ, IL-6, G-CSF, TNFα IL-8, IL-1ra, and GM-CSF emerged as the most promising cytokines to be further investigated for treatment of BD- and VKH-associated uveitis." (PMID 32210963, 2020). "Our data suggest that the aetiology-specific inflammatory mediators that are elevated in the disease entities associated with uveitis included in this study are IL-10 in IOL, RANTES and IFN-α2 in ARN, and IL-6, IL-17A, IL-22, and G-CSF in BE." (PMID 32066796, 2020). "The great differences in the concentrations of IP-10, IL-6, and G-CSF between AH from patients with uveitis and HC (at least 20-fold), in the majority of the patients, make them top candidate therapeutic targets as well." (PMID 32210963, 2020). "Overall, each subtype indicated the presence of upregulated IL-6 levels, except the unclassified uveitis subtype (4b1) (SMD = 0.67, 95% CI − 0.45–1.79, P = 0.24)." (PMID 33060644, 2020). "Regardless of aetiology, this report clearly demonstrated that intraocular IL-6 levels were significantly increased in uveitis." (PMID 33060644, 2020). "IL-6 is involved in the differentiation of CD4+ T cells into Th17 cells known to play a pivotal role in uveitis." (PMID 33101305, 2020). "Although a majority of previous investigations have shown higher serum IL-6 levels among uveitis patients than healthy controls, results of ocular fluid observations are less consistent." (PMID 33060644, 2020). "JAK inhibitors block intracellular signal transduction downstream of different cytokine receptors, such as IL-2 and IL-6, and so appear to be an innovative and interesting option in uveitis treatment." (PMID 33171664, 2020). "Interleukin 6 (IL-6), glycoprotein 130, and IL-6 receptor levels are all elevated in uveitis in many studies of sampling of ocular fluids/tissues." (PMID 30886955, 2018). "Further evidence of alternative therapies is needed with evidence of a potential role of anti-interleukin-6 agents in the management of severe refractory uveitis." (PMID 30886955, 2018). "Not surprisingly, there are anecdotal reports of success of using anti-IL-6 therapy in the form of tocilizumab, in refractory uveitis." (PMID 30886955, 2018). "IL-6 can be induced by cytokines such as IFN-γ, TNF-α and IL-1β, which is an important cytokine that causes inflammatory response of uveitis." (PMID 28384257, 2017). "This means that IL-6 levels in BD uveitis in comparison with the control groups was reduced after treatments." (PMID 28468317, 2017). "In experimental ophthalmology, lutein inhibited LPS-induced uveitis in rats and mice and decreased IL-6 levels in the aqueous humor." (PMID 27047687, 2016). "IL-6 is found at elevated levels in the aqueous humour of patients with active uveitis, and has been shown to be upregulated early in the disease process." (PMID 26774505, 2016). "A review of medical records was completed, and aqueous levels of IL-10 and IL-6 from 10 patients with diffuse large B cell vitreoretinal lymphoma and 7 patients with uveitis are reported." (PMID 23750271, 2013). "Although the mean level of IL-6 and IL-10 expression in uveitis vitreous samples differentiated them from tumor samples, overlapping was found in some cases." (PMID 23405064, 2013).
uveitis (continued). "Inversely, the mean IL-6 concentration was lower for PIOL (41.4±35 pg/mL) than for uveitis (1184±2394 pg/mL) samples (P = 0.018)." (PMID 23405064, 2013). "We present a patient with MCD with refractory uveitis that was successfully treated with tocilizumab, a humanized anti-interleukin 6 (IL-6) receptor antibody." (PMID 23198204, 2012). "Blocking IL-6 has been shown to mitigate uveitis in experimental autoimmune uveitis models." (PMID 40124359, 2025). "This study examined only IL-6, but many other inflammatory cytokines may be related to uveitis, and we intend to focus on other cytokines and interleukins in the future." (PMID 38232093, 2024). "IL-6 mainly produced by T cells, B cells and monocytes/macrophages in the eyes with uveitis." (PMID 38232093, 2024). "In addition to being key in the generation of uveitis and subsequent macular edema through these inflammatory pathways, IL-6 also can lead to the development of macular edema through other pathways." (PMID 36902105, 2023). "Moreover, the downregulation of IL-35 expression at the peak of EAU also coincided with the upregulation of proinflammatory cytokines such as TNF-α and IL-6 that initiate and promote pathology in uveitis." (PMID 35897732, 2022). "Several cellular junction proteins maintain the BRB, and during bacterial infection and other ocular inflammation models (e.g., uveitis and glaucoma), increased inflammatory mediators (e.g., IL-6, MIP2, TNF-α, and IL-1β) can impair the barrier properties (24, 62, –, 66)." (PMID 35913202, 2022). "IL-6 and IL-10 are the most extensively studied cytokines in vitreoretinal lymphomas; studies have demonstrated that elevated aqueous humor or vitreous fluid IL-10 and IL-10/IL-6 ratio can help distinguish vitreoretinal lymphomas from uveitis." (PMID 36059608, 2022). "In addition, it has been shown that IL-6 functionally antagonises TGFβ and abolishes immune privilege in eyes with endotoxin-induced uveitis." (PMID 33671954, 2021). "Interleukin 6 is an inflammatory cytokine, which is characteristic of uveitis." (PMID 34439078, 2021). "Inflammatory cytokines, such as IL-6, which transduces cell signaling through the JAK/STAT pathway, and TNF, whose expression is reduced by inhibition of JAK1 and JAK2, are considered to be associated with the pathology of JIA-uveitis and ANA-positive uveitis." (PMID 34627340, 2021). "This hypothesis is supported by the observation that both patients in whom GLM therapy failed rapidly achieved CR of uveitis after switching to anti-IL-6 therapy with tocilizumab." (PMID 34419092, 2021). "We may summarize that the upregulation of inflammatory cytokines plays an important role in the pathophysiology of uveitis, mainly IL-6, as well as IL-1β, IL-2, INFγ, TNFα, IL-10, and GM-CSF." (PMID 33921773, 2021). "The coupled elevation of inhibitory cytokines IL-35 and IL-10 with IL-6 and IL-ll may represent an immunoregulatory response in uveitis." (PMID 33469457, 2020). "TNF-α and IL-6 are important proinflammatory cytokines that mediate the pathogenesis of uveitis." (PMID 33510636, 2020). "In uveitis, IL6 has been proposed to be especially important in HLA-B27 positive cases." (PMID 32458144, 2020). "The exact relationship between IL-6 and Tregs in modulating uveitis is not clearly understood." (PMID 33101305, 2020). "In particular, IL-6 is involved in differentiation of CD-4 cells into Th-17 cells that have been shown to play a significant role in various immune-mediated diseases such as uveitis." (PMID 31523783, 2019). "IL-6 has a variety of proinflammatory biological activities and contributes to the pathogenesis of many ophthalmologic disorders including age-related macular degeneration, diabetic retinopathy, and uveitis." (PMID 26783382, 2015). "IL-6 was detected in 100% of the uveitis samples, IL-10 in 60%, and IFNγ in 48%." (PMID 23405064, 2013).
uveitis (continued). "In conclusion, our study showed that uveitis associated with TB featured increased aqueous levels of IL-6, CXCL2, CXCL8, CXCL9, and CXCL10, which is not typical of an active ocular TB infection." (PMID 22509092, 2012). "In this context, HTLV-1-infected CD4 T-cells collected from patients suffering from uveitis, which is the second-most frequent HTLV-1-associated disease in Japan after HAM-TSP, also produce large amounts of various inflammatory cytokines such as IL-1, IL-6, TNF-α, and IFN-γ." (PMID 41020241, 2025). "Notably, two phase III trials, namely, MEERKAT (NCT05642312) and SANDCAT (NCT05642325), are currently underway to evaluate the efficacy, safety, pharmacokinetics, and pharmacodynamics of vamikibart, an anti-IL-6 monoclonal antibody, in patients with uveitis ME." (PMID 41424786, 2025). "Additionally, elevated inflammatory cytokine levels, such as TNF-α and IL-6 in the aqueous humor of uveitis patients, may contribute to myopia progression." (PMID 39006849, 2024). "In addition, determining IL-6 levels in other cases of uveitis as well enables evaluation of the extent of intraocular inflammation and could thus prove beneficial in selecting treatment options such as tocilizumab." (PMID 35439966, 2022). "The effects of IL-6 in uveitis may be further augmented by ambient intraocular TNF-α and IL-1β." (PMID 34285659, 2021). "Aqueous humor cytokine analysis effectively distinguishes VRL from uveitis, with VRL patients exhibiting significantly higher IL-10 levels and an IL-10/IL-6 ratio >1.55, achieving 94.1% sensitivity and 100% specificity." (PMID 41403850, 2025). "Increased IL-6 levels in intraocular fluid can result from inflammation, and the IL-10/IL-6 ratio is used to differentiate VRL from uveitis." (PMID 40414948, 2025). "Cytokines, including IL-6, TNF-α, IFN-γ, and IL-17, play a central role in the pathogenesis of uveitis." (PMID 39075390, 2024). "In addition, other reports have found elevated IL-6 in macular edema associated with uveitis, and inhibition of IL-6 may be an effective method for treating non-infectious uveitis." (PMID 38232093, 2024). "Herpes and toxoplasmosis are the leading causes of uveitis, and both Th1 and Th17 T cells and cytokines such as IL-6 and TNF-α are involved in the pathogenesis of uveitis." (PMID 36424630, 2022). "Previous investigations have showed the increased expression of circulating CRP, IL-6 and TNF-α in the uveitis." (PMID 36275682, 2022). "In the endotoxin-induced uveitis (EIU) model, TA-NLCs further reduced the ability of other inflammatory cells to secrete other inflammatory factors by influencing the secretion of IL-6." (PMID 36424630, 2022). "When comparing uveitis entities, the B27+ AAU group showed significantly increased levels of IL-2, IL-6, IL-18, IL-22, IL-1β, and interferon (IFN)-γ." (PMID 34783307, 2021). "Psoriatic patients have a higher incidence and prevalence of uveitis, and the involvement of IL-17, IL-23, TNF-α, and IL-6 molecules unite both conditions." (PMID 34829740, 2021). "In this sense, significantly higher levels of TNF-α, IL-6, IL-8, MIP-1α and leukocytes, as well as histological evaluation of EIU group, compared to healthy group confirmed the correct development of the uveitis model." (PMID 34684030, 2021). "In conclusion, we have demonstrated that the aetiology-specific inflammatory mediators elevated in different types of uveitis include IFN-α2 in ARN and IL-6, IL-17A, and G-CSF in BE." (PMID 32066796, 2020). "In order to elucidate the potential mechanism of endotoxin tolerance in uveitis, this study established an endotoxin tolerance model for uveitis and detected the expression of IL-17, INF-γ, and IL-6 in rats' aqueous humor after clinical evaluation." (PMID 32671118, 2020).